NF1 (neurofibromin 1)
Diseases named in the same sentence as NF1 in open-access papers (continued):
Sharing a sentence is not in itself a finding about the gene and the disease.
iris hamartomas (13 papers, 2013 to 2025). "In ophthalmology hamartoma of the iris, termed Lisch nodules, are among the diagnostic criteria of NF1." (PMID 25424184, 2014). "Lesions resembling iris hamartomas, or Lisch nodules, were noted in two of the three NF1 minipigs examined by slit-lamp." (PMID 30302402, 2018). "In contrast, some NF1 hallmarks such as cutaneous neurofibromas (cNFs), café au lait macules (CALMs), and iris hamartomas (Lisch nodules) may manifest later in life and be highly penetrant (>99% at age 20)." (PMID 30479396, 2018).
LEOPARD syndrome (13 papers, 2011 to 2022). "The Leopard Syndrome is an autosomal dominant genetic disease, mainly caused by PTPN11, instead of NF1, mutations." (PMID 32357851, 2020).
metastatic melanoma (13 papers, 2017 to 2024). A melanoma that has spread from its primary site to another anatomic site. "Patients with BRAF and NF1 mutations were the only ones who had brain metastases when metastatic melanoma was diagnosed (12.9%)." (PMID 38339344, 2024). "In conclusion, we here describe transcriptomic signatures found not only in metastatic melanoma tumor cells but also in melanocyte progenitors, melanoblasts, in the case of an NF1 partial loss of function." (PMID 34362135, 2021). "In one report, a patient with triple wild-type (BRAF/NRAS/NF1 WT) metastatic melanoma with two missense mutations in MAP2K1 showed a partial response to MEK inhibitor trametinib, followed by progression of disease after two months." (PMID 32483240, 2020). "We found a significant difference in survival outcome across the genomic subtypes, with the NF1 subtype associated with poor survival in a cohort largely consisting of metastatic melanoma." (PMID 28267273, 2017). "In addition, major signaling pathways such as VEGF, senescence/secretome, endothelin, and cAMP/PKA are likely to be upregulated upon NF1 loss of function in both melanoblasts and metastatic melanoma." (PMID 34362135, 2021). "In all, this suggests that the prognostic significance of harboring NF1 mutation may have a greater impact in the most advanced stages of metastatic melanoma although additional studies in larger cohorts with distant metastatic melanoma patients are needed." (PMID 28267273, 2017). "In conclusion, we reviewed metastatic melanoma’s genetic and biological properties, highlighting the significance of molecular mutations like NRAS, BRAF, NF1, and others in disease progression and treatment responses." (PMID 38534309, 2024). "In metastatic melanoma patients who lack BRAF V600E mutations (including patients with NRAS and NF1 mutation), targeted therapy has shown minimal effectiveness." (PMID 37444637, 2023). "BRAF, NRAS, and NF1 mutational status in metastatic melanoma was not statistically associated with differences in either overall survival or progression-free survival, except for rare patients with BRAF fusions or internal BRAF gene rearrangements." (PMID 37444637, 2023). "Moreover, analysis of multiple clinical trials indicate that the NF1-mutant subtype has the worst outcome among all metastatic melanomas." (PMID 34331013, 2021). "In this report we intended to analyze the NF1-controlled transcriptome and identify regulated signaling pathways in two independent models: NF1+/− induced pluripotent stem cell-derived melanoblasts and their late stage transformed counterpart, NF1+/− metastatic melanoma." (PMID 34362135, 2021). "In addition to MPNSTs, a known NF1 associated malignancy, such a correlation was also observed only in NF1 null metastatic melanoma cell line, MeWo but not wild-type NF1 carrying 92.1 cell line." (PMID 29212209, 2017). "Genetic alterations in BRAF, NRAS and NF1 that activate the ERK cascade, account for over 80% of metastatic melanomas." (PMID 29180761, 2017). "Trametinib is an NF1 inhibitor which is also known as a mitogen-activated protein kinase (MAPK) kinase (MEK) inhibitor with anticancer activity and is FDA approved for use in metastatic malignant melanoma." (PMID 34872356, 2021).
Moyamoya disease (13 papers, 2011 to 2025). Moyamoya disease (MMD) is a rare intracranial arteriopathy involving progressive stenosis of the cerebral vasculature located at the base of the brain causing transient ischemic attacks or strokes. "First, it was shown to be associated with quasi-MMD (syndromic MMD), moyamoya angiopathy with a known comorbidity such as Down syndrome or neurofibromatosis type I (NF1)." (PMID 34381413, 2021). "Intrudingly, MRVI1 mutation was found to increase the risk of developing moyamoya angiopathy in patients with NF1." (PMID 34381413, 2021). "We report a 60-year-old female patient manifesting hypercalcemia due to hyperparathyroidism, a solitary fibrous tumor (SFT) of the pleura, multiple gastrointestinal stromal tumors (GISTs), and moyamoya disease associated with NF1." (PMID 26442164, 2015). "Moyamoya disease is a cerebral vasculopathy that is only rarely observed in association with NF-1, particularly in the pediatric age range." (PMID 21603789, 2011). "There are several reports concerning the association of moyamoya disease and NF1, which could be explained by the close proximity of genes on chromosome 17." (PMID 26442164, 2015). "A 1.8-year-old boy (NF1 c.1307C > A (p.S436*)) with infantile spasm, hypsarrythmia, and developmental arrest was diagnosed with West syndrome and had moyamoya disease and a horseshoe kidney in WBMRI." (PMID 35093157, 2022). "Various diseases, including FMD, developmental RAS, neurofibromatosis type 1 (NF-1), Moyamoya disease, vasculitis such as Takayasu’s disease, Alagille syndrome, Marfan syndrome, and Williams syndrome, are associated with pediatric RVH." (PMID 26564026, 2015). "The disorders we identified were Moyamoya disease (MMD), COL4A1, COL4A2 pathogenic variant, Ehlers–Danlos syndrome (E-D), neurofibromatosis type 1 (Nf1), sickle cell disease (SCD), cerebral cavernous malformations (CCM), hereditary hemorrhagic telangiectasia (HHT) and Marfan syndrome." (PMID 38790247, 2024). "Clinical entities with cerebral vasculature pathology can first emerge in childhood, such as Moyamoya disease or genetic defects such as Neurofibromatosis type 1 (NF-1), where progressive narrowing of central cerebral vasculature results in progressive ischemic brain injury." (PMID 34122310, 2021). "Moreover, NF-1 is associated with cerebrovascular diseases, pathologic vasculature, and moyamoya disease, and therefore the incidence of intratumoral hemorrhage in NF-1 patients might differ from that of sporadic PA." (PMID 35626817, 2022). "Here, we report the results of treating an NF1 patient with the coexistence of multiple GISTs of the gastrointestinal tract, SFT of the pleura, hyperparathyroidism, and moyamoya disease." (PMID 26442164, 2015). "NF1 has been reported to be associated with a number of neoplasms; however, to the best of our knowledge, the coexistence of NF1, SFT, GIST, and moyamoya disease has not been previously reported." (PMID 26442164, 2015).
osteoporosis (13 papers, 2011 to 2025). A condition of reduced bone mass, with decreased cortical thickness and a decrease in the number and size of the trabeculae of cancellous bone (but normal chemical composition), resulting in increased fracture incidence. "Approximately 20–50% of NF-1 patients have osteoporosis, which is associated with alterations in bone transformation biochemical markers, including decreased serum 25-hydroxyvitamin D and elevated serum PTH levels." (PMID 41170329, 2025). "Although osteopenia/osteoporosis have been reported in NF1, pathophysiology and correlations with underlying genetic defect are poorly understood." (PMID 35288591, 2022). "Collectively, these data implicate the M-CSF/c-Fms signaling axis as a critical pathway underlying the aberrant functioning of Nf1 haploinsufficient osteoclasts and warrant further investigation of c-Fms as a potential therapeutic target for treating NF1 associated osteoporosis and osteopenia." (PMID 23144792, 2012). "Also, osteoclasts play a critical role in potentiating osteolytic activity, cooperating with Nf-1-deficient mesenchymal cells and osteoblasts to engender multiple NF-1-associated osseous defects, including osteoporosis, in transgenic mouse models closely recapitulating human disease." (PMID 31577713, 2019). "Collectively, these results implicate the M-CSF/c-Fms signaling axis as a critical pathway underlying the aberrant functioning of Nf1 haploinsufficient osteoclasts and may provide a potential therapeutic target for treating NF1 associated osteoporosis and osteopenia." (PMID 23144792, 2012). "It is well known that NF-1 affects bone quality (osteoporosis) and quantity (vertebral body dysplasia)." (PMID 34814912, 2021). "Unfortunately, this investigation did not provide unambiguous results on the effects of vitamin D3/ alendronate combination on NF1-related osteoporosis patients because of the low number of enrolled individuals." (PMID 33066259, 2020). "In a subsequent study, 6 patients with NF1-related osteoporosis were enrolled to evaluate the efficacy of vitamin D3 treatment in combination with alendronate." (PMID 33066259, 2020). "However, fertility is reduced, puberty is delayed, and osteoporosis appears to occur more frequently than expected in men with NF1 suggesting defects in gonadal function or endocrine regulation." (PMID 30571760, 2018). "Additionally, NF1 subjects also showed low BMD consistently with osteopenia or osteoporosis." (PMID 33066259, 2020). "In addition, a higher than expected occurrence of osteoporosis has been reported in men with NF1, which may reflect alterations in the production of testicular hormones." (PMID 30571760, 2018). "Similarly, in a mouse model of NF1, serum levels of total TGF-β1 in Nf1 conditional knockout mice have been found to be significantly increased compared to wild type mice and have been associated with multiple skeletal abnormalities, such as osteoporosis and impaired fracture healing." (PMID 35054138, 2022). "Although our patient was not examined for osteoporosis or osteopenia with a DEXA scan, the loss of neurofibromin 1 was undoubtedly involved in his orthopaedic manifestations and presentations." (PMID 23936704, 2013).
Marfan syndrome (12 papers, 2014 to 2025). A disorder of the connective tissue. "Congenital meningoceles are rare and typically associated with disorders such as NF1 and Marfan syndrome." (PMID 41357572, 2025). "Each of these disorders has well-established major causative genes: PKD1 and PKD2 for ADPKD, FBN1 for Marfan syndrome, and NF1 for NF1 disease." (PMID 41411243, 2025). "PERADIGM identified additional candidate genes associated with ADPKD-related and Marfan syndrome-related phenotypes, some of which are supported by existing literature, and demonstrated enhanced signal detection for NF1-specific phenotypes beyond traditional methods." (PMID 41411243, 2025). "For instance, Autosomal Dominant Polycystic Kidney Disease (ADPKD) is primarily attributed to pathogenic variants in the PKD1 and PKD2 genes, while Marfan syndrome and Neurofibromatosis type 1 (NF1) are mainly associated with the FBN1 and NF1 genes, respectively." (PMID 41411243, 2025). "Renal artery stenosis may also occur in association with NF1, Williams' syndrome, Marfan's syndrome, congenital Rubella syndrome, Kawasaki disease, and Crohn’s disease." (PMID 24678641, 2014). "We evaluated PERADIGM on three rare diseases: ADPKD, Marfan syndrome, and NF1 using data from the UK Biobank." (PMID 41411243, 2025). "Spontaneous vertebral AVF is extremely rare and is associated with a variety of vascular dysplastic disorders such as NF-1, fibromuscular dysplasia, and Marfan's syndrome." (PMID 33815242, 2021). "The heterogeneity of findings on IBA within Marfan syndrome, NF1, EDS, and LDS does not give clear direction to genetic counselors." (PMID 27743245, 2017).
multiple endocrine neoplasia type 1 (12 papers, 2012 to 2024). An autosomal dominant tumor predisposition syndrome caused by pathogenic variants in the MEN1 gene, characterized by an increased risk of tumors of the parathyroid glands, pituitary gland, and foregut neuroendocrine tumors (most commonly pancreatic islet cells). "NENs comprise at least ten recognized inherited NEN syndromes, including multiple endocrine neoplasia type 1 and 2 (MEN-1 and MEN-2), von Hippel–Lindau syndrome (VHL) and neurofibromatosis type 1 (NF1)." (PMID 31443481, 2019).
pulmonary stenosis (12 papers, 2014 to 2025). "This mutation was previously reported associated to NF1 with pulmonary stenosis and in two NF1 patients with mild phenotype." (PMID 35885913, 2022). "Spinal scoliosis, pulmonary stenosis, and learning difficulty appeared to occur at relatively similar frequencies between p.Met992del and the wider NF1 cohort." (PMID 34897289, 2022). "On the contrary, a male with CALMs, joint laxity, frontal bossing, macrocephaly, pulmonary stenosis and no lentigines at the age of 5, suspected to be affected by NS, received diagnosis of NF1 after the molecular analysis (firstly performed because of the number of CALMs = 6)." (PMID 24767283, 2014).
acral melanoma (11 papers, 2017 to 2026). "KIT mutations were detected exclusively in three acral lentiginous melanomas (10%); in one case it was found in association with a NF1 mutation and in another with a NRAS mutation." (PMID 33917086, 2021). "The two observed NF1 mutations were a p.G453D missense and p.K1345* nonsense unreported mutations, detected in a nodular melanoma and in an acral lentiginous melanoma, respectively." (PMID 33917086, 2021). "Strikingly, the study of acral melanoma also identified recurrent driver mutations in RTK/RAS signaling genes, including PTPN11, KIT, NF1, KRAS, and NRAS, all of which are recurrent in human AML (and commonly associated with NPM1c mutations)." (PMID 40773291, 2025). "In acral melanoma, BRAF (9%), NRAS (17%), KRAS (8%), KIT (19%), and NF1 (7%) mutations were detected." (PMID 39564955, 2024). "BRAF and NRAS mutations are common in acral melanocytic nevus, whereas acral melanoma shows lower rates of KIT, NF1, BRAF, and NRAS mutations and remarkable copy number variations in genes such as CCND1, CDK4, hTERT, PAK1, and GAB2." (PMID 35997352, 2022). "TERT promoter mutations were found in 4 cases (13%): two acral lentiginous melanomas also harbored a BRAF mutation, another a NRAS mutation, while a nodular melanoma harbored a NF1 mutation." (PMID 33917086, 2021). "There are several mutations occurring in acral melanoma that we did not identify in acral naevi, including NF1, KIT, and TERT promoter alterations, recently reported in 15%, 12%, and 11% of acral melanomas, respectively." (PMID 30995742, 2019). "Considering we detected no recurrent non-V600E BRAF, KIT, or NF1 mutations in naevi, this may imply that acral melanomas harboring these mutations arise primarily de novo, whereas BRAF V600E or NRAS Q61 mutant acral melanomas may more frequently arise from pre-existing naevi." (PMID 30995742, 2019). "All acral melanomas displaying TERT copy number gains were also all BRAF wild type, but overlapped with N/KRAS and NF1 alterations." (PMID 29156643, 2017). "In acral melanoma, BRAF and NRAS are still the most frequent mutations present (although less frequent than in non-acral cutaneous melanoma), followed by NF1 and KIT mutations." (PMID 30995742, 2019). "Recurrent non-V600E BRAF, KIT, NF1, and TERT promoter mutations, present in acral melanoma, were not identified." (PMID 30995742, 2019). "As in cutaneous and acral melanoma, the mutational profile categorizes MM into different molecular groups: BRAF-mutated; RAS-mutated; NF1-loss; and triple wild-type (absence of mutations in BRAF, RAS and NF1; but the presence of KIT mutations and/or amplifications)." (PMID 37773078, 2023).
colon carcinoma (11 papers, 2014 to 2025). "Studies by Seminog and Goldacre determined that patients with pathogenic mutations in the NF1 gene have a higher risk of colon cancer compared to the general population, supporting our findings in the patient analyzed." (PMID 40458721, 2025). "Additionally, considering cancers that are more common in the general population, and NF1 cohort, elevated risk for colon cancer was found." (PMID 35927360, 2022). "Three participants in the NF1 group were excluded due to inflammatory bowel disease (n = 2) or colonic cancer (n = 1)." (PMID 28814319, 2017). "APC, SMAD4, NF1 (neurofibromin 1), ARID5B, NCOR1 (nuclear receptor corepressor 1), IGFR1R (insulin like growth factor 1 receptor) and GNAS (GNAS complex locus) were the most often mutated genes in patient-derived colon cancer cells." (PMID 33050525, 2020). "APC, SMAD4 (SMAD family member 4), NF1 (neurofibromin 1), ARID5B, NCOR1 (nuclear receptor co-repressor 1), IGFR1R (insulin like growth factor 1 receptor) and GNAS (GNAS complex locus) were the most often mutated genes in patient-derived colon cancer cells, YUMC-C1 and YUMC-C2." (PMID 33050525, 2020).
Down syndrome (11 papers, 2011 to 2025). "In this study, we focused on syndromic disorders caused by seven tumor suppressor genes: FH, NF1, PTCH1, RB1, STK11, and TSC1/2." (PMID 40702147, 2025). "Down syndrome and NF1 were also observed together, as well as a pathogenic de novo variant of NF1 and de novo deletion of chromosome 20q11.23." (PMID 36831560, 2023). "The number of patients with associated SCD, NF1, Down syndrome, cranial radiation, congenital cardiac abnormality, renal artery stenosis, ACTA2 mutation, and Alagille syndrome were 131 (42.5%), 47 (15.3%), 40 (13.0%), 24 (7.8%), 18 (5.8%), 6 (1.9%), 3 (1.0%), and 3 (1.0%), respectively." (PMID 36752913, 2023).
endometrial cancer (11 papers, 2011 to 2026). Primary or metastatic malignant neoplasm involving the endometrium (mucous membrane that lines the endometrial cavity). "This case serves as a paradigm for mechanism-driven precision oncology, illustrating that everolimus monotherapy can achieve durable clinical benefit in NF1-deficient recurrent endometrial cancer, with remission persisting even after treatment discontinuation." (PMID 42266657, 2026). "In addition, we previously revealed that chromosomal imbalances in the Ras-PI3K pathway genes (NF1, PTEN, K-Ras, and PIK3CA) are also common in endometrial cancer, indicating that the Ras-PI3K pathway is activated in the majority of endometrial cancers." (PMID 22662154, 2012). "There was no family history of NF1, although the maternal great grandmother had endometrial cancer in her early forties." (PMID 21637783, 2011).